Y_RNA (Y RNA )
Gene: Miscellaneous RNA gene on chromosome 1 (175,022,479 to 175,022,580, reverse strand). Ensembl gene ENSG00000206659.
Homologues: Orthologues: chimpanzee Y_RNA (100% identical), guinea pig Y_RNA (95% identical), macaque Y_RNA (93% identical), guinea pig Y_RNA (92% identical). Paralogues in human: RNY3 (93% identical), Y_RNA (93% identical), Y_RNA (92% identical), Y_RNA (91% identical), RNY3P1 (90% identical), Y_RNA (90% identical), RNY3P14 (89% identical), Y_RNA (89% identical), RNY3P16 (88% identical), Y_RNA (88% identical), RNY3P11 (87% identical), Y_RNA (87% identical), and 97 more.